TNF (tumor necrosis factor)
Diseases named in the same sentence as TNF in open-access papers (continued):
Sharing a sentence is not in itself a finding about the gene and the disease.
atherosclerosis (continued). "Using the multivariate analysis, a significant association between TNF-α and IL- 1( levels, and a higher chance of atherosclerosis development in HIV group were observed." (PMID 31664319, 2020). "Atherosclerosis is a chronic inflammatory disease of the arterial wall, driven by immune cells and cytokines at all stages, and, TNF-deficient mice have reduced plaque size." (PMID 32805626, 2020). "Tumor necrosis factor-alpha (TNF-α), a secretory inflammatory cytokine expressed from macrophages and VSMCs, is one of the major proinflammatory cytokines associated with atherosclerosis and is known to promote proliferation and migration of VSMCs6." (PMID 32286430, 2020). "For example, increased TNF-α expression is associated with the deterioration of renal function in uremia and IL-6 is related to the promotion of muscle wasting and atherosclerosis." (PMID 30795639, 2019). "High concentrations of TNF-α in serum have been associated with Alzheimer disease, atherosclerosis and frailty." (PMID 31830086, 2019). "In particular, TNFα has been implicated in the pathogenesis of atherosclerosis; for example, the disruption of TNFα has been reported to delay the progression of atherosclerosis and to reduce lesion sizes." (PMID 31735914, 2019). "TNF-α is known to be a risk factor of inflammatory vascular disorders, such as atherosclerosis and preeclampsia, which are associated with VSMC dysfunction." (PMID 30765689, 2019). "In contrast to eNOS, AT1R, when activated by angiotensin II and atherosclerosis-inducing factors such as TNFα and VCAM1 causes hypertension through vasoconstriction." (PMID 30643517, 2018). "A study demonstrated that in apolipoprotein E-deficient (apoE−/−) mice, levels of TNF-α expression are closely associated with lesions in atherosclerosis-prone sites." (PMID 30524759, 2018). "In particular, TNF levels have been found to be significantly up regulated in mice prone to developing atherosclerosis and levels of TNF were directly linked to SAA increase SAA plasma." (PMID 30597899, 2018). "Several studies have reported an association between an increased atherosclerosis-related inflammation markers [(e.g. TNF-α and an increased risk of neurodegenerative diseases, including stroke, dementia and PD." (PMID 29552322, 2018). "Dietary supplementation of EGCG counteracted several adverse effects associated with vascular inflammation and atherosclerosis, including decreased secretion of inflammatory cytokines such as IL-6 and TNF-α." (PMID 29593532, 2018). "Many factors (e.g., angiotensin II, tumor necrosis factor alpha (TNF-α)) that play the main role in pathogenesis of atherosclerosis have been shown to cause mitochondrial damage." (PMID 28777310, 2017). "Inflammation has been reported as a vital factor in causing atherosclerosis in particular, induced by inflammatory cytokines such as interleukin-1 (IL-1), tumor necrosis factor α (TNF-α), and interferon-γ (IFN-γ)." (PMID 30460305, 2017). "TNF-α-mediated inflammation in vascular smooth muscle cells is believed to be a major mechanism underlying the pathophysiology of atherosclerosis." (PMID 28556814, 2017). "Tumor necrosis factor-α (TNF-α), one of the most potent inflammatory cytokines, is closely associated with atherosclerosis." (PMID 28348463, 2017). "SIRT6 has not only been reported to protect against liver fibrosis, atherosclerosis, osteoarthritis, and arthritis but has also been associated with increased TNF production and the development of autoimmune encephalomyelitis and cerebral ischemia." (PMID 28894448, 2017). "Injection of TNF-α into mice caused changes of physiological functions of VECs and VSMCs; those changes, together with others, initiated atherosclerosis." (PMID 27167346, 2016). "IL-10 global knock out mice exhibit unregulated inflammatory activity, which is exemplified by enhanced TNF accumulation and thus is associated with a variety of pathogenic outcomes including atherosclerosis." (PMID 26808574, 2016).
atherosclerosis (continued). "In this context, TNF-α (hereto referred as TNF), produced largely by activated monocytes/macrophages, is known to be negatively associated with restenosis and atherosclerosis." (PMID 26808574, 2016). "Macrophage-associated cytokines such as TNF-α, IL-1β, and IL-6 have emerged as key factors in the pathogenesis of atherosclerosis." (PMID 27281478, 2016). "We elected to focus on IL‐18, IL‐33, and TNF, because these cytokines have been implicated in the pathology of both atherosclerosis and RA." (PMID 26749303, 2016). "In this context, the tumor necrosis factor (TNF)-α activates NF-κB signaling transduction what is considered involved in the pathogenic of atherosclerosis." (PMID 27846846, 2016). "The major cause of atherosclerosis and other vascular diseases is chronic vascular inflammation and is initiated by proinflammatory cytokines such as TNF-α." (PMID 27366195, 2016). "Its activity has been associated with atherosclerosis.Additionally, NF-κB regulates the expression of a number of genes involved in celladhesion and inflammation including IL-6, TNF-α, E-selectin, vascular cell adhesionmolecule-1, ICAM-1, and L-selectin." (PMID 26397969, 2015). "The proinflammatory, pleiotropic, and homotrimeric soluble cytokine TNF-α is implicated in some metabolic disorders with an inflammatory background including, but not limited to, atherosclerosis." (PMID 25959742, 2015). "CD160 engagement by both classical and non-classical MHC-I molecules mediates NK cell cytotoxicity and proinflammatory cytokine production of a unique profile (IFN-γ, TNF-α, and IL-6), all of which have been implicated in atherosclerosis." (PMID 26071079, 2015). "Systemic inflammation, and TNF specifically, have been suggested to influence the metabolic dysregulation, atherosclerosis, and higher risk for cardiovascular disease associated with RA." (PMID 26036272, 2015). "Cytokines such as IL-1β, IL-18, IL-6 and TNF-α are key mediators in chronic vascular inflammatory response underlying several aspects of atherosclerosis and cardiovascular disease." (PMID 26600018, 2015). "Mice deficient in TNF-α develop less atherosclerosis than those with intact TNF-α expression (i.e., apoE−/− single knockout)." (PMID 24968272, 2014). "TNF-α-induced inflammatory responses and procoagulant activity have been implicated in the pathogenesis of vascular diseases including atherosclerosis and myocardial infarction." (PMID 25162582, 2014). "CX3CL1, which has a major pathogenic role during atherosclerosis, was detected in aneurysmal adventitia where it is produced by vascular endothelial cells such as BECs in response to TNFα." (PMID 24587165, 2014). "Pathogenic effects of PMNs in atherosclerosis are mediated through production of pro-inflammatory cytokines [IL-8, tumor necrosis factor alpha (TNFa)] and reactive oxygen species." (PMID 24629144, 2014). "Hyperproduction of inflammatory markers such as C-reactive protein, interleukin-1 (IL-1), interleukin-6 (IL-6) and tumour necrosis factor-α (TNF-α) can be considered risk factors and some are directly related to the severity of atherosclerosis." (PMID 24642982, 2014). "By simultaneously adding LDL and TNF-α, which mimic the important risk factors of atherosclerogenesis: hyperlipidemia and inflammation, we can now reproduce several features of atherosclerosis in culture." (PMID 24010774, 2013). "On the other hand, the dysregulation of TNF-α production has been implicated in several of human diseases, as well as in atherosclerosis and cancer." (PMID 23651618, 2013). "Previous studies revealed that elevated levels of TNF-α and IL-1β in patients with CVD have been detected, indicating that TNF-α and IL-1β are two important cytokines in vascular inflammation and highly associated with atherosclerosis." (PMID 23895132, 2013). "Elevated TNFα levels have been observed and associated with conditions such as atherosclerosis and coronary heart disease resulting from C. pneumoniae infection." (PMID 23527290, 2013).
atherosclerosis (continued). "Due to the relevance of TNFα in the inflammatory pathway of RA, several polymorphisms of this cytokine have been evaluated as a potential risk factors for atherosclerosis occurrence in this setting." (PMID 23024462, 2012). "The aim of our study was to assess the serum levels of adipokines (adiponectin, leptin, resistin, and TNF-α) in patients with PAOD caused by atherosclerosis." (PMID 22547903, 2012). "The levels of adipokines (adiponectin, leptin, resistin, and TNF-α) in patients with PAOD caused by atherosclerosis were successfully investigated." (PMID 22547903, 2012). "All of these data suggest the significant inverse relationship between level of adiponectin and IL-6 or TNF-α associated with the development of inflammation-related atherosclerosis." (PMID 21829524, 2011). "Atherosclerosis was ameliorated in gAd Tg apoE-deficient mice, which was associated with decreased expression of class A scavenger receptor and TNF." (PMID 21829524, 2011). "In apolipoprotein-E deficient mice, which provide a valid research model for atherosclerosis, inactivation of the gene encoding TNFα significantly reduces the size of atheroma plaques." (PMID 17335569, 2007). "Additionally, systemic inflammation in asthma, driven by cytokines like IL-6, IL-13 and TNF-α, has been linked to endothelial dysfunction and vascular damage, key processes in atherosclerosis." (PMID 40332077, 2025). "The therapeutic efficacy of SIN in the context of DN is mediated through pivotal signaling pathways, such as the tumor necrosis factor (TNF) signaling pathway, the cytosolic DNA-sensing pathway, and pathways associated with lipid metabolism and atherosclerosis, among other contributory pathways." (PMID 40732224, 2025). "KEGG pathway enrichment analysis identified 176 pathways, with the top 20 including the TNF signaling pathway, IL-17 signaling pathway, Th17 cell differentiation, and disease-associated pathways such as lipid and atherosclerosis, AGE-RAGE signaling in diabetic complications, and pathways in cancer." (PMID 40634403, 2025). "Pro‐inflammatory macrophages in particular initiate and sustain tissue inflammation by producing inflammatory cytokines such as IL‐6 or TNF‐α,24 among which IL‐6 particularly has been reported to be associated with enhanced inflammation in the context of atherosclerosis." (PMID 39909868, 2025). "Similarly, variations in the promoter region of the TNF-α gene can influence TNF-α production, affecting the risk of atherosclerosis and other inflammatory conditions." (PMID 39812546, 2025). "In addition, chronic low-grade inflammation, particularly involving IL-6, interleukin 8 (IL-8), and TNF-α, is considered to be associated with the pathogenesis of hypertension and atherosclerosis." (PMID 40034990, 2025). "In addition, TNF-α and IL-6 can also promote the formation of foam cells, which increases the risk of atherosclerosis in RA patients." (PMID 38731567, 2024). "Secondly, there is evidence from multiple studies that elevated levels of RC are associated with low-grade inflammation and may be linked to tumor necrosis factor, interleukin-1, 6, and 8, as well as adhesion molecules that facilitate atherosclerosis." (PMID 39135721, 2024). "TNF-α is an important risk factor for atherosclerosis, as it impairs endothelial cell function." (PMID 36103099, 2024). "Systemic inflammation, a hallmark of atherosclerosis, likely plays a crucial role, with elevated inflammatory markers such as interleukin-6, tumor necrosis factor-α, and highly sensitive c-reactive protein contributing to oxidative stress and endothelial dysfunction." (PMID 39272707, 2024). "Therefore, we investigated the molecular mechanisms underlying the effect of miR-19a-3p on TNF-α-induced atherosclerosis and shear stress-induced endothelial cells." (PMID 39080547, 2024). "Meanwhile, TNF-α was found to be associated with atherosclerosis." (PMID 39104857, 2024).
atherosclerosis (continued). "Analogous tactics may be employed for additional pro-inflammatory cytokines, like IL-6 and TNF-α, which are also implicated in intensifying the inflammatory cascade in atherosclerosis." (PMID 39712846, 2024). "We also found that TERT knockdown increased atherosclerosis-associated phenotypes, as indicated by increased TNF-α and ADRP protein levels and increased cellular lipid accumulation, as determined using the BODIPY probe, compared with those in the con siRNA+OA+Met group." (PMID 39223261, 2024). "The tumor necrosis factor alpha (TNF-α), identified as a critical mediator in the inflammatory pathway, is closely linked to the pathogenesis of numerous cardiovascular diseases, including atherosclerosis." (PMID 38792249, 2024). "Since TNF-α activates the NF-κB pathway, which contributes to atherosclerosis, targeting this signaling pathway may help prevent the risk of developing the disease." (PMID 39858429, 2024). "Previous findings also demonstrated that TNF-α, a major proinflammatory cytokine implicated in atherosclerosis development, induced the endothelial-mesenchymal transition (EndMT) in human umbilical vein endothelial cells (HUVEC), resulting in the impairment of endothelial barrier function." (PMID 37628753, 2023). "Compared with young people, the elderly have significantly increased plasma inflammatory markers associated with vascular diseases such as atherosclerosis, including TNF-α, interleukin-1β (IL-1β), interleukin-6 (IL-6), C-reactive protein (CRP), interferon γ (IFN-γ), MCP-1, and MMPs." (PMID 37894840, 2023). "Likewise, inflammation markers such as interleukin-6 (IL-6) and tumor necrosis factor (TNF) are independently associated with adverse cardiac outcomes in people with atherosclerosis." (PMID 37639046, 2023). "Raised inflammatory cytokines like TNF-α and deficient IL-10 lead to severe atherosclerosis." (PMID 36763189, 2023). "Plasma levels of TNF and adhesion molecules are associated with subclinical atherosclerosis." (PMID 37834170, 2023). "Excessive ox-LDL in the body can trigger an inflammatory response, activate macrophages, and up-regulate the expressions of pro-inflammation cytokines (such as IL-1β and TNF-α), which ultimately causes endothelial cell damage and atherosclerosis plaque formation." (PMID 36557935, 2022). "In addition to apoptosis, endothelial cell senescence is positively associated with the development of atherosclerosis, and exposure to TNF-α promotes premature endothelial senescence." (PMID 36060429, 2022). "Furthermore, proinflammatory cytokines, such as IL-6 and tumor necrosis factor-α, have been implicated in the progression of atherosclerosis and type 2 diabetes." (PMID 35352134, 2022). "Genes involved in fluid shear stress and atherosclerosis include IL1β, TNF, MMP9, AKT1, and NOX4; genes associated with AGE-RAGE signaling pathway in diabetic complications include AKT1, IL1β, and NOX4; while genes associated with HIF signaling pathway contain STAT3, NOX4, NFκB, and MAPK1." (PMID 36192741, 2022). "Atherosclerosis progression, as a chronic inflammatory mechanism, is characterized by immune system dysregulation associated with increased pro-inflammatory cytokine production, including interleukin 6 (IL-6), tumor necrosis factor-α (TNF-α), and IL-1β." (PMID 36274722, 2022). "Likewise, inhibition of TNF-α reduces experimental atherosclerosis, but long term inhibition of TNF-α in patients increases the risk for opportunistic infections and non-melanoma skin cancers." (PMID 35252400, 2022). "Our results showed that the Cur+Bai combination also effectively reduced the level of TNF-α in the blood vessel tissue, the production of which is associated with the Fluid shear stress and atherosclerosis KEGG pathway and pathological progression of diabetic angiopathy." (PMID 36060932, 2022).
atherosclerosis (continued). "TNF-α, both an inducer and target of NF-κB increased ROS formation, apoptosis and endothelial dysfunction in rat carotid arteries, while TNF-α inhibition resulted in vasculo-protective effects, suggesting an association between NF-κB activation and ageing associated atherosclerosis." (PMID 35846362, 2022). "In addition, the pro-apoptotic protein Bax and atherosclerosis-associated cytokines (interleukin-1β, interleukin-6, and tumor necrosis factor-α) were significantly downregulated, whereas the anti-apoptotic protein Bcl-2 was upregulated." (PMID 35137664, 2022). "Others have shown that IL-1, IL-6, and TNF-a are associated with atherosclerosis in general, and therefore, may be elevated in patients with cardiac or cerebrovascular diseases." (PMID 36582735, 2022). "TNF encodes a multifunctional proinflammatory cytokine that plays a key role in mediating the inflammatory response in atherosclerosis, including induction of the expression of various cell adhesion molecules, monocyte/macrophage migration, and local proliferation." (PMID 35571620, 2022). "Atherosclerosis is reduced in mice with TNF-α-deficient B cells; B cells-derived TNF-α is a key cytokine that promotes atherosclerosis development through augmenting macrophage TNF-α production to induce cell death and inflammation that promote plaque vulnerability." (PMID 35748536, 2022). "However, the subclinical atherosclerosis-associated plasmatic signature in the HIVneg population was different and marked with the upregulation of TNF-α and IL-27 and downregulation of CCL26 and IL-17C (p=0.02, 0.043, 0.011 and 0.021, respectively)." (PMID 33936102, 2021). "In addition, these HP strains can trigger a strong inflammatory reaction by releasing a huge amount of cytokines such as interleukin-1 (IL-1), interleukin-1 (IL-6), and tumor necrosis factor-α (TNF-α) free radicals causing oxidative stress and atherosclerosis." (PMID 34216301, 2021). "Moreover, in aged patients, including centenarians, high levels of TNF-α in the blood were associated with a high prevalence of atherosclerosis." (PMID 35052582, 2021). "Hypertriglyceridemia is linked to atherosclerosis, increased production of pro-inflammatory cytokines including tumor necrosis factor-α (TNFα) and interleukin-6 (IL6), and may alter the function of the blood–brain barrier (BBB)." (PMID 34915908, 2021). "In an animal experiment investigating the pathological effect of TNF-α on atherosclerosis, it was found that when the TNF-α gene was deficient, the expression levels of adhesion molecules and chemokines were altered and led to the inhibition of the development of atherosclerosis." (PMID 34071276, 2021). "Moreover, ox-LDL is strongly associated with the pathogenesis of atherosclerosis and its uptake via macrophages results in the release of TNF-α." (PMID 33673027, 2021). "TNF has been linked to endothelial injury, endothelial apoptosis, and impairment of endothelial progenitor cells, partly through reactive oxygen and nitrogen intermediates, resulting in recruitment of inflammatory cells leading to atherosclerosis progression." (PMID 34988343, 2021). "Tumor necrosis factor-α (TNF-α) is a primary pathogenic mediator of EC activation and also a major prototypic proinflammatory cytokine derived from activated monocytes/macrophage, which is mainly related to the pathogenesis of atherosclerosis." (PMID 34858081, 2021). "Moreover, elevated IL-6 levels and TNF-α have been associated with the development of atherosclerosis and vascular calcification in CKD patients." (PMID 35052582, 2021). "While the development of atherosclerosis was associated with increased plasma levels of IL-1β, TNFα, IL-6, monocyte chemoattractant protein-1 (MCP-1), and C-C motif chemokine ligand-5 (CCL-5), increased MCP-1 and CCL-5 were specifically observed in SCI mice versus uninjured controls." (PMID 34571804, 2021).